ENSG00000290971 (novel transcript)
Synonyms: ANKRD20A3; ANKRD20A3P; LOC642929
Gene: Long non-coding RNA gene on chromosome 9 (66,109,394 to 66,179,552, reverse strand). Ensembl gene ENSG00000290971.
Diseases named in the same sentence as ENSG00000290971 in open-access papers:
ENSG00000290971 is named in the same sentence as 1 disease in open-access papers, as found by Europe PMC text mining. Sharing a sentence is not in itself a finding about the gene and the disease.
ENSG00000290971 shares sentences with these, for which no sentence is quoted: cancer (1 paper).